TAF11L8 (TATA-box binding protein associated factor 11 like 8)
Tractability: No criterion of Open Targets' tractability assessment is met for any kind of drug.
Gene: Protein-coding gene on chromosome 5 (17,590,364 to 17,590,960, reverse strand). Ensembl gene ENSG00000283967.
Gene Ontology:
Molecular function: RNA polymerase II general transcription initiation factor activity; protein heterodimerization activity
Biological process: RNA polymerase II preinitiation complex assembly; transcription initiation at RNA polymerase II promoter
Cellular component: transcription factor TFIID complex; nucleus
Homologues: Orthologues: tropical clawed frog taf11 (45% identical), zebrafish taf11 (45% identical), Drosophila melanogaster Taf11 (42% identical), Caenorhabditis elegans taf-11.1 (33% identical), Caenorhabditis elegans taf-11.2 (27% identical). Paralogues in human: TAF11L10 (100% identical), TAF11L5 (100% identical), TAF11L6 (100% identical), TAF11L7 (100% identical), TAF11L3 (99% identical), TAF11L4 (99% identical), TAF11L9 (99% identical), TAF11L13 (95% identical), TAF11L2 (92% identical), LINC02218 (88% identical), TAF11L12 (87% identical), TAF11L11 (85% identical), and 2 more.